PVALB (parvalbumin)
Diseases named in the same sentence as PVALB in open-access papers (continued):
Sharing a sentence is not in itself a finding about the gene and the disease.
psychiatric disorder (26 papers, 2011 to 2025). A disorder characterized by behavioral and/or psychological abnormalities, often accompanied by physical symptoms. "Loss of parvalbumin (PV) expressing neurons (PV neurons) is relevant to the underlying mechanisms of the pathogenesis of neurological and psychiatric diseases associated with the dysregulation of neuronal excitatory networks and brain metabolism." (PMID 39349423, 2024). "Overall, we found 28 distinct genes (out of 285 GWAS genes, 9.8%) that were upregulated in PVALB from the TL and robustly associated (GWAS p < 10-8) with psychiatric disease." (PMID 38864245, 2024). "Interneurons that express the calcium binding protein parvalbumin (PV) have been implicated in multiple psychiatric disorders, including AD, in which post mortem studies have confirmed a robust (over 50%) decrease in hippocampal parvalbumin." (PMID 37108357, 2023). "Increasing evidence suggests that parvalbumin (PV) interneurons play a key role in the cognitive process, whereas the dysfunction of these interneurons has been implicated in a number of major psychiatric disorders." (PMID 26416717, 2015). "Increasing evidence has suggested that parvalbumin (PV) interneurons are required for the synchronization of neural activities and higher brain processes, whereas its dysfunction is implicated in many psychiatric disorders." (PMID 32019903, 2020). "We conclude that alterations to the inhibitory system are consistently identified in animal models of psychiatric disorders and, more specifically, that mutations affecting the function of parvalbumin-positive interneurons seem to play a central role in the symptoms observed in these disorders." (PMID 29375819, 2018). "Hence, the functional defect of parvalbumin might have a profound causal relationship with the development of psychiatric disorders." (PMID 34955723, 2021). "Parvalbumin (PV) interneurons play critical roles in cortical processing and have been implicated in FXR1-linked mental illnesses." (PMID 39753370, 2025). "Since these psychiatric disorders are observed in perturbation of executive functions, parvalbumin expression in the human prefrontal cortex has been preferentially analyzed accordingly." (PMID 34955723, 2021). "A popular theory suggests that dysregulation of fast-spiking parvalbumin interneurons (PV INs) and elevated excitation-inhibition (E-I) balance contribute to the pathophysiology of various psychiatric disorders." (PMID 32029441, 2020). "In particular, alteration of parvalbumin-expressing neurons, a gamma-aminobutyric acid (GABA)ergic neuronal subpopulation, has been suggested to be associated with psychiatric disorders." (PMID 23347699, 2013). "Accordingly, disruptions of PNNs in neurodegenerative and psychiatric diseases may affect the synaptic balance on parvalbumin-expressing interneurons and their electrophysiological properties." (PMID 37143468, 2023). "Furthermore, the expression of psychiatric disorder-related molecules, especially parvalbumin, is significantly decreased by thyroid hormone insufficiency during the perinatal period." (PMID 34955723, 2021). "Altered functioning of GABAergic interneurons expressing parvalbumin (PV) in the basal ganglia-thalamo-cortical circuit are likely to be involved in several human psychiatric disorders characterized by deficits in attention and sensory gating with dysfunctional decision-making behavior." (PMID 33536607, 2021). "Our data indicate that post-adolescent NMDAR deletion, even in a wider cell population than parvalbumin-positive interneurons, is also not sufficient to generate behavioral abnormalities resembling psychiatric disorders." (PMID 34899420, 2021).
neurological diseases (14 papers, 2014 to 2025). "In line with previous findings, Miro1 knockout impaired mitochondrial transport into presynaptic regions of parvalbumin interneurons or motor neurons, resulting in rapidly progressing neurological diseases and death within weeks." (PMID 40176126, 2025). "Parvalbumin interneurons play a fundamental role in numerous neurological diseases, with a high probability of activity-regulated disinhibition or degeneration of these cells in the CN and thus the inhibitory function of these cells." (PMID 39062188, 2024). "Parvalbumin is related to the occurrence of various clinical diseases and age-related cognitive deficits and nervous system disorders." (PMID 37895432, 2023). "Importantly, in many other models of neurological diseases, selective vulnerability of parvalbumin-positive interneurons has been reported." (PMID 41008554, 2025). "Ten proteins showed co-localization with a neurological disease using both plasma protein abundance and plasma mRNA abundance (SIRPA, CTSH and CD33 with AD; and ASF1A, FCRL3, VEGFB, TYMP, PVALB, LMAN2 and CD5 with MS)." (PMID 40037332, 2025). "Neurological disorders in humans and mice involving IP3R1, calbindin (CB), parvalbumin (PV), and other calcium signaling proteins." (PMID 25653583, 2014). "In a post-mortem study of five human cases without neurological diseases we investigated the y-group, INC and RIMLF for the presence of parvalbumin and CR positive neurons including their co-expression." (PMID 26696837, 2015).
neurodevelopmental disorder (12 papers, 2017 to 2025). A behavioral and cognitive disorder with onset during the developmental period that involves impaired or aberrant development of intellectual, motor, or social functions. "Changes in parvalbumin-positive interneurons in particular are commonly reported in studies of patients with neurodevelopmental disorders or in associated animal models." (PMID 31417418, 2019). "Mouse dysbindin genetic defects and other mouse models of neurodevelopmental disorders share defective GABAergic neurotransmission and, in several instances, a loss of parvalbumin-positive interneuron phenotypes." (PMID 28344592, 2017). "It is unclear in many reports of parvalbumin neuronal loss in clinical cases or animal models of injury/neurodevelopmental disorders whether the deficit is actually in the number of parvalbumin interneurons or in the expression of the parvalbumin protein within the neurons." (PMID 31417418, 2019). "Parvalbumin interneurons (PVIs) are disrupted across diverse neurodevelopmental disorders, highlighting their vulnerability to developmental perturbations." (PMID 41415393, 2025).
brain disorder (8 papers, 2019 to 2025). A disease affecting the brain or part of the brain. "Of these, parvalbumin-type (PV neuron) dysfunction is a feature of several sex-biased psychiatric and brain disorders, although, the underlying developmental mechanisms are unclear." (PMID 38503929, 2024). "Parvalbumin interneurons are therefore candidate key players involved in mechanisms underlying the pathogenesis of brain disorders associated with both neuronal networks’ dysfunction and brain metabolism dysregulation." (PMID 34616292, 2021). "This may have important implications for changes in pain perception in brain disorders that impact on the strength of cortical gamma and function of parvalbumin interneurons, such as schizophrenia." (PMID 30816113, 2019). "Evidence suggests that signal intensity and the number of parvalbumin (PV)-expressing interneurons and perineuronal nets (PNN) is reduced in a variety of brain disorders including AD." (PMID 36529803, 2022). "In the context of this mini-review, we have highlighted recent advances supporting the implication of prominent ER and cytosolic Ca2+ regulators (i.e., SERCA2, IP3Rs, RyRs, PVALB, NNAT) in the neurobiology of brain disorders with a strong neurodevelopmental component." (PMID 36875674, 2023). "Subgenual anterior cingulate cortex (sgACC) of human subjects without brain disorders were labeled using fluorescent in situ hybridization (FISH) for CRH and markers of excitatory (SLC17A7), inhibitory (GAD1) neurons, as well as markers of other interneuron subpopulations (PVALB, SST, VIP)." (PMID 35280164, 2022).
tumor (7 papers, 2007 to 2026). "Taken together, these results indicated that the BRAFV600E/AktDD tumor parenchyma comprises lower fractions of parvalbumin- and somatostatin-positive interneurons." (PMID 36538906, 2022). "We also detected the effect of ionomycin or parvalbumin on the anti-tumor activity of TNFα in a mice model." (PMID 29506556, 2018). "CHRC is consistently positive for parvalbumin and calcium-binding protein expressed in the distal nephron, a feature further suggesting a histogenetic relationship between this tumor and the intercalated ducts." (PMID 17711572, 2007). "Moreover, considering the differences observed in the peritumoral region and also the fact that the migration of somatostatin and parvalbumin is controlled by different signaling pathways during brain development, its final position may be also controlled by different effects from tumor tissue." (PMID 36538906, 2022). "Our data demonstrated a reduction of the fraction of parvalbumin- and somatostatin-expressing interneurons in the BRAFV600E/AktDD tumor parenchyma also in the GG mouse model." (PMID 36538906, 2022). "Other groups have described these changes at length, and they include reduced levels of parvalbumin interneurons, decreased expression of KCC2, tumor-mediated glutamate release, and reduced glutamate uptake." (PMID 31731042, 2020). "In contrast to parvalbumin and beta-lactoglobulin, EL and human alpha-lactalbumin are both found in high content in horse and human milk, respectively, as is OA, which may be indicative that, apart from their anti-tumor activity, both complexes also carry out bactericidal function in the milk." (PMID 24260444, 2013). "The corresponding results demonstrated that the fractions of parvalbumin-expressing cells in this area and the tumor parenchyma itself were not significantly different (online suppl." (PMID 36538906, 2022).
infection (6 papers, 2012 to 2021). The state of being infected such as from the introduction of a foreign agent such as serum, vaccine, antigenic substance or organism. "In contrast, PVALB+ HCLCs were detected in the OHC region after Ad-Atoh1 infection and all of them were Tm-red+." (PMID 35082601, 2021). "Our finding was a bit unexpected as decreased number of parvalbumin neurons have previously been reported in other prenatal infection models, e.g., in the hippocampus of mice offspring exposed to poly I:C at GD9 as well as rat offspring exposed poly I:C at GD15." (PMID 23349891, 2013). "In mice in which this reporter is used to visualize cells expressing Cre under control of the parvalbumin regulatory sequence, cortical injections of DO-GFP rAAV produced a striking drop in TdTomato fluorescence in the infection area." (PMID 22866029, 2012). "Fourteen days after Ad-V5 infection, we did not observe any PVALB+ HCLCs in the OHC region, and the remaining existing IHCs were negative for Tm-red." (PMID 35082601, 2021). "The volume of parvalbumin-positive structures attributed to basket cell terminals was localised on EGFP-positive granule cell somata and taken as a measure for basket cell innervation after infection with an EphA7 knockdown vector." (PMID 27405707, 2016). "We found that prenatal infection reduced the density of parvalbumin- but not somatostatin-positive interneurons in the CA1 area of the hippocampus and strongly reduced the strength of inhibition early during postnatal development." (PMID 22238649, 2012).
neurodegenerative disease (5 papers, 2010 to 2023). A disorder of the central nervous system characterized by gradual and progressive loss of neural tissue and neurologic function. "Given its expression in parvalbumin-expressing neurons and its role in enhancing inhibitory synaptic transmission, it will be important to further investigate the potential role of KChIP1 in mental health and neurodegenerative diseases." (PMID 20678225, 2010).
mitochondrial disease (1 paper, 2023). "In this study, a novel murine model was devised, which harbours mitochondrial dysfunction in parvalbumin-expressing cells, achieved via mtDNA depletion in vivo, recapitulating major neurological impairments observed in mitochondrial disease." (PMID 37872380, 2023).
retinopathy (1 paper, 2020). "Inhibition of STEP with TC-2153 during progressive AMD-like retinopathy (from 9 to 13 months of age) reduced the thickness of the retinal inner nuclear layer, as evidenced by a decreased amount of parvalbumin-positive amacrine neurons." (PMID 32707818, 2020). "Pharmacological inhibition of STEP with TC-2153 for four months during the active progression of AMD-like retinopathy had a negative effect on relative thickness of the retinal INL, as evidenced by a decrease in the amount of parvalbumin-positive amacrine neurons." (PMID 32707818, 2020).
PVALB also shares sentences with these, for which no sentence is quoted: Seizure (4 papers); Encephalopathy (2); experimental autoimmune encephalomyelitis (2); frontotemporal dementia (2); spinocerebellar ataxia 1 (2); Tourette syndrome (2); type 2 diabetes (2); absence seizures (1); Action tremor (1); Alcohol Use Disorder (1); arterial hypertension (1); asthma (1); attention deficit-hyperactivity disorder (1); bacterial infection (1); brain injury (1); carcinoma (1); chronic prostatitis (1); clear cell renal cell carcinoma (1); colon cancer (1); contact urticaria (1); Convulsive status epilepticus (1); cyst (1); dementia (1); developmental and epileptic encephalopathy (1); diabetic neuropathy (1); diabetic retinopathy (1); Down syndrome (1); encephalitis (1); generalized dystonia (1); hematological disease (1).
A further 18 diseases each share a sentence with PVALB in 1 paper.